RB1 (RB transcriptional corepressor 1)
Diseases named in the same sentence as RB1 in open-access papers (continued):
Sharing a sentence is not in itself a finding about the gene and the disease.
cancer (continued). "Transcription of proteins essential for G1-S depends on E2F1-5 proteins and their dimerization partners (pRb, p107, and p130, encoded by RB1, RBL1, and RBL2 respectively); genes encoding these proteins are often dysregulated or mutated in cancer." (PMID 29725503, 2018). "Up to 6% of all human cancers bear mutations in FBXW7, and RB1 alterations occur in about 60–90% of sporadic small cell lung cancer cases, for instance." (PMID 29689640, 2018). "Dysregulation of E2F1 is a frequent event observed in human cancer cells because of the inactivation of the retinoblastoma protein RB1, altered expression of cyclin-dependent kinases or their inhibitors and/or the expression of transforming viral proteins." (PMID 30359437, 2018). "We hope that our data serves as a starting point to further examine cancer vulnerabilities, in particular in FBXW7‐, RB1‐, or NF2‐mutated tumors." (PMID 29689640, 2018). "On the other hand, phosphorylation of retinoblastoma protein 1 (RB1) carried out by CDK4/6 is pivotal in the transition from G1 to S phase in many cancer cells." (PMID 30002440, 2018). "These instances are listed in the Dataset EV2 and they included, among others, RBL2, KLF5, and ARAF as homologs of cancer drivers RB1, PBX1, and BRAF, respectively." (PMID 29572294, 2018). "Aberrant RB1 is known to inhibit development of various cancers through modulating cell cycles, DNA replication and apoptosis." (PMID 28716024, 2017). "Among the enriched genes, CDK1 plays an important role in the cell cycle, while RB1 is a driver gene in several cancer types." (PMID 28567416, 2017). "RB1 status in cancer cells has been reported to be responsible for response to radiation treatment and specific drug therapies." (PMID 28900297, 2017). "The ability of Rb1 and its metabolite compound K to intervene different cellular pathways in CSCs suggests that Rb1 can be a wide spectrum chemopreventive agent for cancer treatment." (PMID 27825116, 2017). "Rb1 has various anti-cancer properties ranging from the inhibition of cell proliferation to angiogenesis as well as in apoptosis induction." (PMID 27825116, 2017).
cancer (continued). "The retinoblastoma gene (RB1) is the first identified tumor-suppressor gene (TSG) that is frequently inactivated in several major cancers." (PMID 28300839, 2017). "Carcinomas arise from transformed epithelial cells and account for 80% of adult malignancies highlighting the need to understand p16/RB1 pathway function in organ epithelia." (PMID 28414317, 2017). "The RB1, a tumor suppressor gene, is a negative regulator of the cell cycle, and its alterations are related to carcinogenesis in several cancers." (PMID 26924873, 2016). "Several well-known cancer driver genes, such as RB1, PTEN and NF1, were suggested to be the targets of the regions." (PMID 27230211, 2016). "Many of the known oncogenes, such as ERBB2, EGFR and CCND1, are frequently amplified and many of the known tumor suppressor genes (TSGs), such as CDKN2A, PTEN, NF1 and RB1, are frequently depleted in various types of cancers." (PMID 27230211, 2016). "In human cancer, the pRB-mediated repression of E2F1 is often disrupted through either inactivating the RB1 gene itself, overactivation of cyclinD-CDK4/6 kinases, or inactivation of CDK inhibitors (CKIs)." (PMID 27036039, 2016). "The transamidation activity of TGM2 has been implicated in apoptosis by interacting with BAX or cross-linking CASP3/Caspase 3 and RB1/pRB to inhibit apoptosis in various cancer cell lines." (PMID 26956429, 2016). "The downstream target of these cell cycle mediators is RB1 (retinoblastoma 1, tumor suppressor) and chemotherapy efficacies were reported to depend on RB1 status in several cancer types." (PMID 26008974, 2015). "For example, ongoing clinical trials are evaluating the use of CDK inhibitors in the treatment of RB1 intact cancers." (PMID 25985759, 2015). "For the RB1 methylation status, only cancer samples presented methylation in the presence of HPV and EBV (60.0%)." (PMID 26032781, 2015). "In such scenarios, temporary inhibition of the RB1 function can potentially lead to the killing of cancer cells or an increase in their sensitivity to radio- or chemotherapeutic agents." (PMID 25755634, 2015). "Our results provide evidence of an Rb1-dependent Ets1-Zeb1 amplification loop that is important in both cancer and in normal development of the thymus." (PMID 25880398, 2015). "Owing to RB1 involvement in many cellular processes, all contributing to its oncosuppressive activity, and considering that its pathway is altered in most human cancers, RB1 represents an appealing target for cancer therapy." (PMID 26160835, 2015). "This can explain why most sporadic cancers have RB1 inactivated because of defects in the pathways that regulate its phosphorylation rather than by mutations." (PMID 26160835, 2015). "Weri-Rb1 is one of the few available cell lines (the other popular one being Y79) for this type of cancer, and remains important for the investigation of demethylation effects induced by treatment." (PMID 26143641, 2015). "In cases with wild-type KRAS, BRAF and PIK3CA a number of cancer-associated genes representing potential drivers were identified (for example, STK11, GNAS, CHEK2 and RB1)." (PMID 25855536, 2015).
cancer (continued). "Consistently, phosphatase activity directed toward RB1 seems to be required for apoptosis induction in cells from different cancer types and the antiapoptotic protein BCL2 can prevent RB1 dephosphorylation and apoptosis." (PMID 26160835, 2015). "We also describe the current antitumoral strategies aimed at the use of RB1 as predictive, prognostic and therapeutic target in cancer." (PMID 26160835, 2015). "A higher frequency of RB1 mRNA downregulation was observed in cancers from treated patients with respect to those from untreated patients." (PMID 26160835, 2015). "The disruption of RB1 is known to be a key pathological event in many cancers and the development of anti-cancer drugs targeting cell cycle regulators, including RB1, is a rapidly growing field." (PMID 24803933, 2014). "This is an important discovery because it is the first report of focal chromothripsis as a mechanism of RB1 gene inactivation in cancer." (PMID 24509483, 2014). "It has been shown that the stage related gene RB1CC1 (RB1-inducible coiled-coil 1) can suppress cell cycle progression and inhibit proliferation through activating the promoter and expression of recurrence related gene RB1 in human cancer." (PMID 23658834, 2013). "Analyzing all the cancer biopsies for RB1 and CtIP/RBBP8 patterns revealed a strong statistically significant correlation between RB1 and CtIP/RBBP8: in more than 90% of those samples in which CtIP/RBBP8 was absent, RB1 was also either absent or reduced." (PMID 24403251, 2013). "We used HCT116 colon-derived carcinoma cells which represent a clinically relevant cancer type for radiation treatment and which express wt RB1." (PMID 22384045, 2012). "In cancer, the RB1 gene is most frequently inactivated through alterations to cyclin dependent kinase regulation, however, in specific cancer types such as small cell lung cancer and retinoblastoma it is uniformly abrogated by direct mutation." (PMID 22417103, 2012). "Our results reveal that miR P-27-5p targets and negatively regulates CDK4, which in turn suppresses RB1 phosphorylation, thereby preventing the progression of cancer cell cycle and promoting G1 arrest." (PMID 22754369, 2012). "Genes such as MYC and PIK3CA, known to be activated in many cancers tend to show more micro-amplifications; others known to be inactivated in cancer such as RB1 and PTEN display comparatively more micro-deletions." (PMID 23284754, 2012). "Rearranged genes showed to be highly connected to well-known altered genes in cancer such as AR, RB1, MYC, and BRCA1." (PMID 22811706, 2012). "The predictive accuracy of RB1 status by the CCND1/CDKN2A ratio was examined with the original 30 cancer cell lines which were used to develop the RB1 gene signature as a training set." (PMID 21447152, 2011). "Expression profiling of 30 cancer cell lines composed of 16 RB1-positive and 14 RB1-negative cancers was performed to find genes that are differentially expressed between the two groups, resulting in the identification of an RB1 signature with 194 genes." (PMID 21447152, 2011). "The gene coding for pRB, Rb1, is a well documented tumor suppressor gene that is frequently inactivated, directly or indirectly, in a wide variety of cancers." (PMID 21544224, 2011). "In accordance with the important role of RB1 as a cell cycle regulator, RB1 deregulation is frequently observed in multiple types of cancers." (PMID 21447152, 2011).
cancer (continued). "A moderate frequency of RB1 dysfunction has been reported in several other types of cancers such as bladder, prostate cancers, and melanoma." (PMID 21447152, 2011). "Accumulating evidence has shown that hypermethylation in the promoter region of CDKN2A or overexpression of CCND1, which results in RB1 dysfunction, frequently occurs in various types of cancers." (PMID 21447152, 2011). "We showed that reduction of KDM5B expression resulted in suppression of cell growth of cancer cells, through co-regulation of the E2F/RB1 cell cycle regulation pathway, and possibly the promotion of apoptosis of cells remaining in sub-G1 phase." (PMID 20226085, 2010). "A similar reduction was found in the ‘HG_U133A’ data set (10 normal mucosa samples and 80 cancers) with the average RB1/E2F3 ratio dropping −0.63-fold (log 2 scale) from normal mucosa to cancer (P=0.019, Student's t-test)." (PMID 19156145, 2009). "Not surprisingly, cytogenetic abnormalities that define human cancers, i.e., BCR-Abl translocations in chronic myelogenous leukemia and RB1 deletions in chronic lymphocytic leukemia have been found in comparable canine cancers." (PMID 19823573, 2009). "A comparison of the RB1/E2F3 transcript ratios revealed a significant reduction of −1.97 fold (log 2 scale) from normal mucosa to cancer (P=8.96 × 10−8, Student's t-test)." (PMID 19156145, 2009). "Cancer susceptibility genes such as retinoblastoma (RB1) and adenomatois polyposis coli (APC) were originally identified as rare, mutant alleles that significantly increase the risk of cancer when inherited through the germ line." (PMID 16495912, 2006). "Since RB1 and other functionally related genes are somatically mutant in so many cancers, study of them should be widely relevant." (PMID 16231982, 2005). "Instead, targeting downstream cancer-specific signatures of the RB1/E2F axis may represent a feasible strategy with higher specificity and fewer adverse effects." (PMID 41492471, 2026). "We found that KLF5 did not affect E2F1 expression, and therefore, we suggest that KLF5 may play a part in promoting cancer by inactivating RB1 by regulating the expression of Cyclin D 1 and XPO1." (PMID 39888288, 2025). "In summary, these data further underscore the hypothesis that RBness cancers phenocopy molecular and clinical characteristics of RB1-defective cancers and therefore could benefit from the same treatment strategies." (PMID 40138429, 2025). "Hence, palbociclib, a selective CDK4/6 inhibitor, for CDK4/6-driven RB1 defects is also a promising option for RBNSig-BC–identified aggressive cancers." (PMID 40138429, 2025). "At genomic level, the majority of somatic CN deletion induces simultaneous deletion of the passenger genes chromosomally adjacent to the driver genes (e.g., RB1), thereby facilitating “collateral lethality” as a new therapeutic strategy to target the neighboring genes for cancer treatment." (PMID 40904703, 2025).
cancer (continued). "This leads us to predict that additional patients exhibiting RBness in the absence of RB1 genomic defects could benefit from existing and next-generation treatment strategies designed for RB1-defective cancers." (PMID 40138429, 2025). "S9H), suggesting the presence of RBness in cancers that lack classical RB1 genetic defects." (PMID 40138429, 2025). "Moreover, the frequency of RB1 alterations increases in tumors that acquired resistance to standard treatment regimens in a variety of cancer types, including CRPC." (PMID 40904703, 2025). "RB1 dysfunction, resulting from mutations, deletions, transcriptional silencing or hyperphosphorylation, significantly contributes to cancer development, particularly in TNBC, where approximately 30% of patients exhibit loss or downregulation of RB1 expression." (PMID 40070134, 2025). "Such patients, and those who present with non-ocular primary malignancies linked to RB1 mutations (e.g., sarcomas, melanomas, or pinealoblastomas), should undergo long-term surveillance for secondary cancers and receive genetic counseling." (PMID 41009976, 2025). "Among all cancer types, RB1 alterations are more commonly identified in treatment‐refractory tumors with neuroendocrine or small‐cell features (e.g., small‐cell lung cancer), which may arise in multiple organs and indicate a poor prognosis." (PMID 40904703, 2025). "In conclusion, the role of RB1 in transcriptional control of PGAMs underscores its importance in remodulating metabolic pathways in both cancer and normal tissue differentiation extending beyond its canonical functions in cell cycle control and differentiation." (PMID 40707487, 2025). "Interestingly, we found the close proximity of NUDT15 and RB1, as well as their frequent somatic codeletions in various cancer types." (PMID 40904703, 2025). "Among them, the tumor suppressor genes CDKN2A and RB1 are frequently inactivated by copy number deletions or point mutations, whereas the oncogenes CDK4, CDK2, CCND1, and CCNE1 are recurrently amplified in the genomes of some human cancers." (PMID 39351198, 2024). "Therefore, elucidating the RB1 pathway and the role of pRB is crucial for understanding the mechanisms of cancer development and for identifying more precise treatment approaches." (PMID 39664374, 2024). "Dysfunctional or deleted RB1 can enhance the proliferation and spread of different cancer types." (PMID 38672640, 2024). "However, data on the effect of RB1 loss on proliferation in HGSC tumors and cancer cell lines are inconsistent." (PMID 38837893, 2024). "As an RB1‐inactive cancer, the protein expression of RB1 in SCLC cells needed to be confirmed." (PMID 39136283, 2024).